SLC25A20 (solute carrier family 25 member 20)
Description:
Mediates the electroneutral exchange of acylcarnitines (O-acyl-(R)-carnitine or L-acylcarnitine) of different acyl chain lengths (ranging from O-acetyl-(R)-carnitine to long-chain O-acyl-(R)- carnitines) with free carnitine ((R)-carnitine or L-carnitine) across the mitochondrial inner membrane, via a ping-pong mechanism (Probable). Key player in the mitochondrial oxidation pathway, it translocates the fatty acids in the form of acylcarnitines into the mitochondrial matrix, where the carnitine palmitoyltransferase 2 (CPT-2) activates them to undergo fatty acid beta-oxidation (Probable). Catalyzes the unidirectional transport (uniport) of carnitine at lower rates than the antiport (exchange).
Synonyms: CAC; CACT
Tractability: Antibody: UniProt predicts a signal peptide or a membrane-spanning region. PROTAC: ubiquitination databases record sites on it; its protein half-life has been measured; a small molecule that binds it is known.
Target class: Electrochemical transporter; Transporter; SLC25 family of mitochondrial transporters; SLC superfamily of solute carriers
Gene: Protein-coding gene on chromosome 3 (48,856,926 to 48,898,904, reverse strand). Ensembl gene ENSG00000178537.
Subcellular location: Mitochondrion inner membrane
Subcellular location (Human Protein Atlas): Cytosol; Mitochondria
Pathways (Reactome):
Metabolism: Carnitine shuttle
Gene Ontology:
Molecular function: carnitine:O-acyl-L-carnitine antiporter activity; protein binding; O-acyl-L-carnitine transmembrane transporter activity
Biological process: carnitine shuttle; carnitine transmembrane transport; mitochondrial transport; O-acyl-L-carnitine transmembrane transport
Cellular component: mitochondrion; mitochondrial envelope; mitochondrial inner membrane
Genetic constraint (gnomAD): Loss-of-function variants: 28 observed, 36.49 expected, observed/expected ratio (o/e) 0.77, 90% interval 0.57 to 1.05. The synonymous counts are far from expectation, so gnomAD's model fits this gene poorly and the ratio says little. Missense variants: 327 observed, 384.01 expected, observed/expected ratio (o/e) 0.85, 90% interval 0.78 to 0.93. Synonymous variants: 101 observed, 141.95 expected, observed/expected ratio (o/e) 0.71, 90% interval 0.61 to 0.84.
Gene-disease validity (ClinGen):
ClinGen rates the evidence that SLC25A20 causes each of these diseases.
carnitine-acylcarnitine translocase deficiency (autosomal recessive): Definitive.
Homologues: Orthologues: chimpanzee SLC25A20 (100% identical), macaque SLC25A20 (99% identical), dog SLC25A20 (96% identical), rabbit SLC25A20 (96% identical), mouse Slc25a20 (93% identical), pig SLC25A20 (92% identical), guinea pig SLC25A20 (92% identical), rat Slc25a20 (91% identical), tropical clawed frog slc25a20 (83% identical), zebrafish slc25a20 (80% identical). Paralogues in human: SLC25A29 (36% identical), SLC25A48 (34% identical), SLC25A45 (34% identical), SLC25A47 (34% identical), SLC25A2 (32% identical), SLC25A15 (32% identical), SLC25A13 (31% identical), SLC25A12 (30% identical), SLC25A39 (28% identical), SLC25A22 (28% identical), SLC25A18 (27% identical), UCP3 (27% identical), and 37 more.
Diseases named in the same sentence as SLC25A20 in open-access papers:
SLC25A20 is named in the same sentence as 74 diseases in open-access papers, as found by Europe PMC text mining. Sharing a sentence is not in itself a finding about the gene and the disease. The quoted sentences say what the papers report.
CACT) deficiency (19 papers, 2018 to 2026). "Carnitine-acylcarnitine translocase deficiency (CACT deficiency) is a rare and life-threatening autosomal recessive disorder of mitochondrial fatty acid oxidation caused by variant of SLC25A20 gene." (PMID 36419912, 2022). "We evaluated three patients, including two siblings, with neonatal-onset CACT deficiency and revealed identical homozygous missense mutations of p.Arg275Gln within the SLC25A20 gene." (PMID 32337051, 2020). "CPT1 deficiency (CPT1D), CPT2 deficiency (CPT2D), and CACT deficiency (CACTD) are rare autosomal inherited recessive disorders, and the causative genes are CPT1A, CPT2, and SLC25A20, respectively." (PMID 35360862, 2022). "Conversely, no variants were found on the SLC25A20 gene, whose mutations are associated with the carnitine-acylcarnitine translocase (CACT) deficiency (MIM 212,138), which is as well a rare autosomal recessive disorder of long-chain fatty acid oxidation." (PMID 38616285, 2024). "Although no individuals in this study were found to carry any variants in SLC25A20, the gene was incorporated into the CCD panel to enable its future application in broader diagnostic settings, ensuring its utility for patients who may present with CACT deficiency in prospective screenings." (PMID 40420233, 2025).
cardiomyopathy (8 papers, 2014 to 2025). A disease of the heart muscle or myocardium proper. "Cardiomyopathy due to SLC25A20 mutations typically manifests in the neonatal period, characterized by rapid progression and high mortality." (PMID 40816837, 2025). "Carnitine-acylcarnitine translocase deficiency resulting from many different mutations in SLC25A20 results in a multi-systemic disorder that includes cardiomyopathy as one of its clinical features (OMIM 212138)." (PMID 30766870, 2019). "Interestingly, the genetic deficiency of SLC25A20 is characterized by cardiomyopathy, decreased cardiac function and arrhythmias in addition to liver dysfunction, skeletal muscle damage and neurologic abnormalities." (PMID 37009793, 2023). "To date, SLC25A20-related cardiomyopathy has been reported almost exclusively in neonates, characterized by rapid progression and high mortality." (PMID 40816837, 2025). "This case highlights the clinical presentation, multimodal imaging findings, and therapeutic response in late-onset SLC25A20-related cardiomyopathy." (PMID 40816837, 2025).
carnitine deficiency (6 papers, 2012 to 2026). "The crucial role of CAC in energy metabolism was demonstrated by the discovery of inherited defects of its gene SLC25A20 causing secondary carnitine deficiency, a syndrome that arises in the very first stage of life as a life-threatening pathology." (PMID 33807231, 2021). "Several studies indicate that mutations in SLC22A5, SLC25A20, CAC genes can cause primary carnitine deficiencies (PCD)." (PMID 33673114, 2021).
Hypoglycemia (5 papers, 2019 to 2023). A decreased concentration of glucose in the blood. "Several clinical studies have also reported that deficiency and/or mutation in SLC25A20 resulted in neonatal hypoglycemia, arrhythmia and sudden death." (PMID 37894945, 2023). "It is pertinent to note that genetic mutations in carnitine-acylcarnitine translocase (encoded by SLC25A20), which mediates the transport of acylcarnitines into the mitochondrial matrix, cause severe metabolic disorders, including hypoglycemia, myopathy, and muscle weakness in humans." (PMID 33944778, 2021).
breast carcinoma (3 papers, 2021 to 2025). "The same was true for other cancer cell types, including glioblastoma, breast cancer, lung cancer, colon cancer, and liver cancer, where SLC25A20 knockdown reduced ATP production by 26-70% at a 40 nM siRNA concentration." (PMID 40521210, 2025). "For example, methylation of SLC25A20 (carnitine/acylcarnitine translocase) in breast cancer cell lines led to accumulation of long chain acylcarnitine species." (PMID 34631530, 2021).
heart failure (3 papers, 2023 to 2025). Inability of the heart to pump blood at an adequate rate to meet tissue metabolic requirements. "Optimized heart failure management, including multimodal therapeutic strategies, may improve cardiac function in patients with SLC25A20-related DCM." (PMID 40816837, 2025).
hepatocellular carcinoma (3 papers, 2021 to 2023). A malignant tumor that arises from hepatocytes. "Furthermore, a study by Yuan at al. found that down-regulation of SLC25A20 promotes hepatocellular carcinoma growth and metastasis through the suppression of fatty acid oxidation." (PMID 37894945, 2023).
Alzheimer disease (2 papers, 2024 to 2025). A progressive, neurodegenerative disease characterized by loss of function and death of nerve cells in several areas of the brain leading to loss of cognitive function such as memory and language. "Consequently, these two genes were excluded, leaving six critical genes with diagnostic significance for Alzheimer’s disease (AD): ACO2, CS, MRPS27, SDHA, SLC25A20, and SYNJ2BP." (PMID 39757625, 2025).
pancreatic cancer (2 papers, 2023 to 2025). "ShRNA-mediated knockdown of SLC25A20 in the pancreatic cancer cell lines SU.86.86 reduced ATP production by 16-60%; however, there was no change in ATP production in pancreatic normal ductal epithelial cells (hTERT-HPNE) after SLC25A20 knockdown." (PMID 40521210, 2025). "The results revealed that shRNA-mediated knockdown of SLC25A20 in the pancreatic cancer cell line MIA PaCa-2 reduced basal respiration by 25-40% and ATP production by 34-43%." (PMID 40521210, 2025). "Additionally, we analyzed the global proteomic changes in pancreatic cancer cell lines treated with SLC25A20 siRNA for 72 h." (PMID 40521210, 2025). "Furthermore, immunostaining of pancreatic cancer tissues from each group revealed a 52% decrease in the expression of p-mTOR in tissues from KPC/ Slc25a20+/- mice compared to KPC mice." (PMID 40521210, 2025). "To evaluate whether SLC25A20 knockdown affects mitochondrial membrane potential in pancreatic cancer cell lines, we measured the potential using TMRE (tetramethyl rhodamine ethyl ester), a cell-permeant, cationic, red-orange fluorescent dye that readily accumulates in active mitochondria." (PMID 40521210, 2025).
diabetes (1 paper, 2025). "Future studies could investigate whether targeting Pdk4, Slc25a20, or other metabolic regulators can restore substrate flexibility and improve coronary microvascular function in diabetes." (PMID 41203872, 2025).
dilated cardiomyopathy (1 paper, 2025). Cardiomyopathy which is characterized by dilation and contractile dysfunction of the left and right ventricles. "Here, we report the first known case of an older adult diagnosed with dilated cardiomyopathy (DCM) harboring the SLC25A20 c.199-10T>G variant." (PMID 40816837, 2025). "A 62-year-old man presented with late-onset dilated cardiomyopathy (DCM) associated with a heterozygous SLC25A20 c.199-10T>G mutation." (PMID 40816837, 2025).
glioma (1 paper, 2023). A benign or malignant brain and spinal cord tumor that arises from glial cells (astrocytes, oligodendrocytes, ependymal cells). "We show that mRNA expression of the prototypical MCT, SLC16A1 (MCT1), for instance, is higher in gliomas compared with corresponding normal brain tissue but otherwise non-discriminatory, while that of SLC25A20 is more emphasised in HGG." (PMID 37490079, 2023).
Hypercholesterolemia (1 paper, 2020). An increased concentration of cholesterol in the blood. "We also found altered DNA methylation in patients with hypercholesterolemia, in key genes associated with fatty acid transport and metabolism (hypomethylated: PPARD, PPARG, SLC27A1, SLC27A3 and SLC25A20, and hypermethylated: ANGPTL4, ACLS6, ACADM and CPT1A)." (PMID 33028190, 2020).
liver dysfunction (1 paper, 2024). "The critical role of the CAC in energy metabolism is underscored by findings that mutations in its gene (SLC25A20) can cause a severe, early-onset disease (secondary carnitine deficiency), characterised by profound cardiomyopathy, respiratory distress, and liver dysfunction." (PMID 39334924, 2024).
motor neuron degeneration (1 paper, 2025). "SLC25A20 and FDX1 emphasized mitochondrial lipid biosynthesis and catabolism, while COA3 linked to mitochondrial genetic information processing and protein translation, suggesting broader biogenesis defects in motor neuron degeneration." (PMID 40864790, 2025).
Sepsis (1 paper, 2020). Sepsis is defined as life-threatening organ dysfunction caused by a dysregulated host response to infection. "Importantly, gene expression of PPARα and downstream genes was also increased after pemafibrate in livers of CLP mice 24 h post‐sepsis initiation, with many genes reaching expression levels close to those seen in vehicle‐treated sham mice (only Acsl1 and Slc25a20 are shown, Fig EV3C and D)." (PMID 31916705, 2020).
sudden cardiac arrest (1 paper, 2019). Unexpected rapid natural death due to cardiovascular collapse within one hour of initial symptoms. "The protein coded by LPCAT1 is involved in the remodelling of phospholipids and has been associated with risk of sudden cardiac arrest, whereas the protein coded by SLC25A20 is involved in the transport of fatty acids across the mitochondrial membrane." (PMID 30841568, 2019).
uveitis (1 paper, 2025). An inflammatory process affecting a part of or the entire uvea. "Machine learning nominated HLX and SLC25A20 as core biomarkers, demonstrating robust diagnostic accuracy in discovery (AS AUC: 0.688/0.700; uveitis AUC: 0.867/0.838) and validation cohorts (AS AUC: 0.653/0.667; uveitis AUC: 0.662/0.736)." (PMID 40929101, 2025). "Intersection of machine learning results across AS and uveitis cohorts identified HLX and SLC25A20 as core diagnostic biomarkers, with both genes demonstrating significant upregulation in disease groups (p < 0.05)." (PMID 40929101, 2025). "In conclusion, this study successfully identifies HLX and SLC25A20 as core biomarkers linking AS and uveitis." (PMID 40929101, 2025). "Overall, our study offers worthy insight into the interconnected molecular pathways of AS and uveitis, and emphasizes the potential of HLX and SLC25A20 as diagnostic markers and targeted treatment approaches for patients suffering from these circumstances." (PMID 40929101, 2025). "To identify core regulatory genes shared between AS and uveitis, we first intersected genes from WGCNA-derived disease-associated modules and cross-disease DEGs, yielding five candidate genes: SORL1, TLR8, HLX, SLC25A20, and IGSF6." (PMID 40929101, 2025). "The findings from our study highlight the critical role of HLX and SLC25A20 as potential cross-disease biomarkers that bridge AS and uveitis." (PMID 40929101, 2025). "HLX and SLC25A20 emerge as immunologic regulators bridging AS and uveitis pathogenesis." (PMID 40929101, 2025). "Parallel analysis in uveitis identified HLX and SLC25A20 as consensus biomarkers across LASSO, SVM-RFE, and Random Forest, validated through multi-algorithm intersection." (PMID 40929101, 2025).
cancer (9 papers, 2015 to 2025). A tumor composed of atypical neoplastic, often pleomorphic cells that invade other tissues. "Proteome analysis revealed that SLC25A20 knockdown reduced cancer cell growth significantly due to inactivation of mTOR via decreased ATP production, ultimately leading to cell death." (PMID 40521210, 2025). "The intra-tumor level of ATP measured in the xenograft model showed an approximate 50% decrease in ATP production by PDAC cancer cells in which SLC25A20 was knocked down." (PMID 40521210, 2025). "To elucidate how the reduction in intracellular ATP production following SLC25A20 knockdown regulates cancer cell growth, we performed proteomics analysis of SU.86.86 cells using LC-MS/MS at 48 h post-knockdown." (PMID 40521210, 2025). "SLC25A20 is frequently downregulated in cancer, which leads to a suppression of β-oxidation of fatty acids, promoting tumor growth and metastasis." (PMID 40563592, 2025). "SLC25A20 knockdown showed that the accumulation of acyl-carnitines in cancer cells." (PMID 40521210, 2025). "Thus, in cancer cells, SLC25A20 has shown potential to inhibit FAO as an independent target of CPT1A, emerging as a promising strategy to inhibit FAO." (PMID 40521210, 2025). "We knocked down SLC25A20 in cancer cells and added glutamine to test whether the decreased ATP levels were restored." (PMID 40521210, 2025). "However, the expression and biological functions of SLC25A20 remain largely unexplored in human cancers, especially in HCC." (PMID 33824298, 2021). "SLC25A20 had a lower expression in 8 cancer types compared with those of normal samples." (PMID 31828117, 2019). "Therefore, we knocked down SLC25A20 in cancer cells to inhibit FAO and tested whether tumor growth driven by an HFD is inhibited." (PMID 40521210, 2025). "This implies that cancer cells depend on medium chain (MC) fatty acids for FAO to generate ATP and that MC fatty acids translocate to the mitochondria via SLC25A20." (PMID 40521210, 2025). "We also knocked down SLC25A20 in SU.86.86 and MIA PaCa-2 cancer cells using shRNA and then implanted the cells into mice fed an RD." (PMID 40521210, 2025). "The reason why research on SLC25A20 and the development of inhibitors have been behind the priority is that FAO of cancer cells was considered to be the same as that of normal cells, leading to CPT1A being targeted as the primary target." (PMID 40521210, 2025). "Our present study also showed that SLC25A20 down-regulation significantly suppressed fatty-acid oxidation in HCC cells, implying that cancer cells may suppress FAO to save more fatty acid in order to grow and divide." (PMID 33824298, 2021). "No studies have been performed in cancer to investigate copy number or gene expression alterations of SLC25A20, a transport protein present in the mitochondrial membrane." (PMID 26444668, 2015).